ZPR1 (ZPR1 zinc finger)
Description:
Acts as a signaling molecule that communicates proliferative growth signals from the cytoplasm to the nucleus. It is involved in the positive regulation of cell cycle progression. Plays a role for the localization and accumulation of the survival motor neuron protein SMN1 in sub-nuclear bodies, including gems and Cajal bodies. Induces neuron differentiation and stimulates axonal growth and formation of growth cone in spinal cord motor neurons. Plays a role in the splicing of cellular pre-mRNAs. May be involved in H(2)O(2)-induced neuronal cell death.
Synonyms: ZNF259; GKAF
Tractability: PROTAC: ubiquitination databases record sites on it; its protein half-life has been measured.
Gene: Protein-coding gene on chromosome 11 (116,773,799 to 116,788,046, reverse strand). Ensembl gene ENSG00000109917.
Subcellular location: Nucleus; Nucleus, nucleolus; Nucleus, gem; Nucleus, Cajal body; Cytoplasm, perinuclear region; Cytoplasm; Cell projection, axon; Cell projection, growth cone
Subcellular location (Human Protein Atlas): Vesicles
Gene Ontology:
Molecular function: protein binding; translation initiation factor binding; protein folding chaperone; translation elongation factor binding; receptor tyrosine kinase binding; zinc ion binding
Biological process: axon development; cellular response to epidermal growth factor stimulus; DNA replication; positive regulation of cell cycle; positive regulation of gene expression; positive regulation of protein import into nucleus; positive regulation of RNA splicing; pre-mRNA catabolic process; apoptotic process involved in development; Cajal body organization; DNA endoreduplication; microtubule cytoskeleton organization; negative regulation of motor neuron apoptotic process; positive regulation of growth; protein folding; regulation of myelination; signal transduction; spinal cord development; trophectodermal cell proliferation; inner cell mass cell proliferation
Cellular component: Cajal body; cytoplasm; Gemini of Cajal bodies; nucleolus; nucleoplasm; nucleus; axon; growth cone; neuronal cell body; perikaryon; perinuclear region of cytoplasm
Genetic constraint (gnomAD): Loss-of-function variants: 33 observed, 54.13 expected, observed/expected ratio (o/e) 0.61, 90% interval 0.46 to 0.81. The upper end of that interval is the gene's LOEUF score, 0.81, which puts it in group 3 of 6, group 1 being the genes least tolerant of losing a copy. Missense variants: 506 observed, 553.2 expected, observed/expected ratio (o/e) 0.91, 90% interval 0.85 to 0.98. Synonymous variants: 187 observed, 205.42 expected, observed/expected ratio (o/e) 0.91, 90% interval 0.81 to 1.03.
Homologues: Orthologues: chimpanzee ZPR1 (99% identical), macaque ZPR1 (96% identical), guinea pig ZPR1 (90% identical), mouse Zpr1 (90% identical), dog ZPR1 (90% identical), rabbit ZPR1 (90% identical), pig ZPR1 (90% identical), rat Zpr1 (89% identical), tropical clawed frog zpr1 (69% identical), zebrafish zpr1 (68% identical), Drosophila melanogaster Zpr1 (47% identical), Caenorhabditis elegans W03F9.1 (39% identical).